RNF115 (ring finger protein 115)
Description:
E3 ubiquitin-protein ligase that catalyzes the 'Lys-48'- and/or 'Lys-63'-linked polyubiquitination of various substrates and thereby plays a role in a number of signaling pathways including autophagy, innate immunity, cell proliferation and cell death. Plays a role in the endosomal trafficking and degradation of membrane receptors including EGFR, FLT3, MET and CXCR4 through their polyubiquitination. Participates together with BST2 in antiviral immunity by facilitating the internalization of HIV-1 virions into intracellular vesicles leading to their lysosomal degradation. Also possesses an antiviral activity independently of BST2 by promoting retroviral GAG proteins ubiquitination, redistribution to endo-lysosomal compartments and, ultimately, lysosomal degradation. Catalyzes distinct types of ubiquitination on MAVS and STING1 at different phases of viral infection to promote innate antiviral response. Mediates the 'Lys-48'-linked ubiquitination of MAVS leading to its proteasomal degradation and ubiquitinates STING1 via 'Lys-63'-linked polyubiquitination, critical for its oligomerization and the subsequent recruitment of TBK1. Plays a positive role in the autophagosome-lysosome fusion by interacting with STX17 and enhancing its stability without affecting 'Lys-48'- or 'Lys-63'-linked polyubiquitination levels, which in turn promotes autophagosome maturation. Negatively regulates TLR-induced expression of proinflammatory cytokines by catalyzing 'Lys-11'-linked ubiquitination of RAB1A and RAB13 to inhibit post-ER trafficking of TLRs to the Golgi by RAB1A and subsequently from the Golgi apparatus to the cell surface by RAB13.
Synonyms: ZNF364; BCA2; Rabring7; CL469780; ZFP364
Tractability: PROTAC: UniProt records ubiquitination sites on it; ubiquitination databases record sites on it.
Gene: Protein-coding gene on chromosome 1 (145,738,868 to 145,824,095, reverse strand). Ensembl gene ENSG00000265491.
Subcellular location: Cytoplasm; Nucleus; Endoplasmic reticulum; Golgi apparatus
Subcellular location (Human Protein Atlas): Mitochondria; Nucleoli
Pathways (Reactome):
Immune System: Antigen processing: Ubiquitination & Proteasome degradation
Gene Ontology:
Molecular function: protein binding; ubiquitin protein ligase activity; ubiquitin-protein transferase activity
Biological process: negative regulation of epidermal growth factor receptor signaling pathway; negative regulation of toll-like receptor signaling pathway; protein autoubiquitination; protein K11-linked ubiquitination; ubiquitin-dependent protein catabolic process via the multivesicular body sorting pathway; protein K48-linked ubiquitination; protein K63-linked ubiquitination; protein polyubiquitination; protein ubiquitination
Cellular component: cytoplasm; endoplasmic reticulum; Golgi apparatus; nucleus; cytosol
Genetic constraint (gnomAD): Loss-of-function variants: 15 observed, 19.11 expected, observed/expected ratio (o/e) 0.79, 90% interval 0.52 to 1.21. The upper end of that interval is the gene's LOEUF score, 1.21, which puts it in group 5 of 6, group 1 being the genes least tolerant of losing a copy. Missense variants: 275 observed, 270.13 expected, observed/expected ratio (o/e) 1.02, 90% interval 0.92 to 1.12. Synonymous variants: 94 observed, 95.63 expected, observed/expected ratio (o/e) 0.98, 90% interval 0.83 to 1.17.
Homologues: Orthologues: chimpanzee RNF115 (99% identical), macaque RNF115 (99% identical), rat Rnf115 (93% identical), mouse Rnf115 (93% identical), pig RNF115 (86% identical), guinea pig RNF115 (85% identical), tropical clawed frog rnf115 (75% identical), zebrafish rnf115a (63% identical), zebrafish rnf115b (49% identical). Paralogues in human: RNF126 (45% identical), RNF181 (16% identical).
Diseases named in the same sentence as RNF115 in open-access papers:
RNF115 is named in the same sentence as 36 diseases in open-access papers, as found by Europe PMC text mining. Sharing a sentence is not in itself a finding about the gene and the disease. The quoted sentences say what the papers report.
breast cancer (21 papers, 2012 to 2024). A primary or metastatic malignant neoplasm involving the breast. "RNF115 is highly expressed in invasive breast cancer and the levels of RNF115 are positively associated with ER levels in the tissue arrays of breast cancer." (PMID 35844553, 2022). "Large scale genome wide-associated studies have identified two variants rs12405132 and rs17354678 at 1q21.1 where RNF115 is located as new susceptibility loci for breast cancer, though it is unclear how the variants affect RNF115 or other genes for the progression of breast cancer development." (PMID 35844553, 2022). "Moreover, high expression of RNF115 is associated with regional recurrence, lymph node metastasis, and unfavorable prognosis in breast cancer." (PMID 32980859, 2020). "In addition, RNF115 directly interacts with and promotes ubiquitination and degradation of p21 and knockdown of p21 partially rescues cell growth arrest caused by knockdown of RNF115 in ER+ breast cancer cells." (PMID 35844553, 2022). "It has been recently reported that the deubiquitinase USP9X and RNF115 are correlatively upregulated in breast cancer tissue arrays and breast cancer cell lines." (PMID 35844553, 2022). "Soon after the release of the complete human genome sequence, the human RNF115 gene has been mapped to chromosome 1q21.1 where frequent chromosomal imbalances have been reported in breast cancer." (PMID 35844553, 2022). "Because RNF115 is upregulated in breast cancer cells and tissues and negatively correlated with lymph nodes metastasis and disease-free survival for regional recurrence, the roles of RNF115 in cell growth and migration have been intensively investigated." (PMID 35844553, 2022). "Analyses with the bulk-seq database suggest that high expression of RNF115 is correlated with poor prognosis in gastric, ovarian and breast cancers, adrenocortical carcinoma, acute myeloid leukemia and kidney chromophobe." (PMID 35844553, 2022). "RING finger protein 115 (RNF115), also known as breast cancer associated gene 2 (BCA2) and Rab7-interacting RING finger protein (Rabring7), has been identified as a highly expressed protein in breast cancer cells and tissues." (PMID 35844553, 2022). "It has been found that RNF115 is highly expressed in breast cancer cells and co-expressed with the estrogen receptor (ER) in more than 70% ER-positive invasive breast ductal carcinomas." (PMID 35844553, 2022). "RNF115 is a novel substrate for USP9X, and the USP9X–RNF115 axis is involved in aggressive phenotypes by increasing breast cancer cell invasion and migration." (PMID 34575114, 2021). "The expression of RNF115 significantly affects the cell growth and progression in breast cancer, and it is substantially correlated with estrogen receptor positive status." (PMID 33509267, 2021). "Previous study has reported that a novel RNF115, whose E3 ligase activity is stabilized by ubiquitin-specific protease 9X, is overexpressed in breast carcinomas." (PMID 33509267, 2021). "RNF115 is highly expressed in ERα-positive breast cancer cell lines and tumors, and positively regulates the growth of breast cancer cells." (PMID 32980859, 2020). "RNF115 has been reported to be overexpressed in >50% of invasive breast tumors, and is important for regulating breast cancer cell proliferation, migration, and invasion." (PMID 32980859, 2020). "Mechanistic investigations reveal that RNF115 promotes breast cancer cell proliferation through targeting the cyclin-dependent kinase inhibitor p21Waf/Cip1 for ubiquitin-dependent degradation." (PMID 32980859, 2020). "Since RNF115 is associated with a positive ERα status in breast cancer specimens, a general importance of ERα for the regulation of RNF115 expression in breast cancer can be assumed." (PMID 27224909, 2016). "In addition, knockdown of RNF115 or inhibition of AKT sensitizes metformin-mediated growth inhibition of multiple breast cancer cell lines." (PMID 35844553, 2022).
breast cancer (continued). "Moreover, RNF115 has been demonstrated to accelerate the breast cancer cell proliferation possessing estrogen receptor α partly by suppressing p21 expression via ubiquitin-mediated degradation." (PMID 33509267, 2021). "Interestingly, USP9X enhances the stability of a E3 ubiquitin ligase, RNF115, which has also been shown to promote cell proliferation in ERα+ breast cancers via downregulation of p21." (PMID 34575114, 2021). "The high expression of RNF115 is also connected with more than half of the invasive breast cancer cases, for which it dynamically participates in regulating the cell proliferation and tumor progression in breast cancer." (PMID 33509267, 2021). "RNF115 is also a target of the PI3K/AKT pathway, which, in breast cancer cells, keeps the expression of this protein high by preventing its proteosomal degradation." (PMID 27224909, 2016). "Upregulation of E3 ubiquitin ligase RNF115/BCA2—also known as Rab7-interacting RING finger protein (Rabring7), widely expressed in various tissues—is observed in different carcinomas, including breast cancer, lung cancer, and gastric cancer and is negatively correlated with prognosis." (PMID 38129372, 2023). "Interestingly, estrogen treatment significantly upregulates the RNF115 mRNA in a dose-dependent manner in ER-positive T47D and MCF7 breast cancer cells as well as in ER-negative MDA-MB-231 cells stably transfected with ER, whereas knockdown of ER substantially impairs the RNF115 mRNA levels." (PMID 35844553, 2022).
lung adenocarcinoma (10 papers, 2021 to 2025). A carcinoma that arises from the lung and is characterized by the presence of malignant glandular epithelial cells. "RNF115 (Ring Finger Protein 115) encodes an E3 ubiquitin ligase; its dysregulation promotes oncogenic signaling, proliferation, and invasion in lung adenocarcinoma." (PMID 41154602, 2025). "In contrast, there are discrepancies for the roles of RNF115 in lung cancer, as high RNF115 mRNA levels are associated with an improvement in overall survival of lung cancer and poor overall survival of lung adenocarcinoma." (PMID 35844553, 2022). "RNF115 has been identified as a regulator in lung adenocarcinoma, where it promotes cellular growth and metabolism while suppressing apoptosis." (PMID 38376606, 2024). "RNF115 is correlated with the prognosis of patients with lung adenocarcinoma or invasive breast cancer." (PMID 36199791, 2022). "In lung adenocarcinoma, RNF115 could ubiquitinate APC and result in its degradation, thus regulating Wnt/β‐Catenin signalling to promote cellular proliferation." (PMID 37132043, 2023). "There are reports on the relationship between RNF115 and lung adenocarcinoma (LAC)." (PMID 35132330, 2022). "Moreover, RNF115 overexpression promotes ubiquitination of adenomatous polyposis coli (APC) to modulate the Wnt/β-catenin pathway activation, and thereby promotes the proliferation and inhibits the apoptosis of lung adenocarcinoma cell lines." (PMID 35844553, 2022).
invasive breast carcinoma (8 papers, 2009 to 2022). A carcinoma that infiltrates the breast parenchyma. "RNF115 has been shown highly expressed in invasive breast cancers and genome-wide association studies have identified RNF115 as a susceptible locus for breast cancer." (PMID 33139700, 2020). "RNF115 was identified as a binding partner of Rab7, involved in endosomal sorting of EGFR and is highly expressed in invasive breast cancers." (PMID 36281581, 2022).
breast tumors (7 papers, 2008 to 2021). "RNF115 is broadly overexpressed in ERα-positive breast tumors." (PMID 32513106, 2020). "Although the oncogenic functions of RNF115 have been revealed in breast tumor cells, the effect of RNF115 on lung cancer is still not clear." (PMID 33509267, 2021). "BCA2 has been characterized as an ubiquitin E3 ligase, RING-finger protein (RNF115), or Rab7-interacting RING-finger protein (Rabring7) that is overexpressed in more than 50 percent of breast tumors, including ER-negative breast cancers." (PMID 28536406, 2015).
viral infection (6 papers, 2017 to 2023). "A previous report suggests that RNF115/BCA2 negatively regulates the NF-κB pathway in 293 T cells treated by viral infection." (PMID 38129372, 2023). "Later, it has been demonstrated that RNF115 catalyzes ubiquitination of a series of proteins to modulate a number of signaling pathways, and thereby regulates viral infections, autoimmunity, cell proliferation and death and tumorigenesis." (PMID 35844553, 2022). "To examine the role of RNF115 in host defense against viral infection in vivo, we infected the Rnf115+/+ and Rnf115−/− mice by intraperitoneal (i.p.)injection of SeV or intravenous (i.v.)injection of EMCV or HSV-1 followed by various analyses." (PMID 33139700, 2020). "Because MAVS is essential for virus infection-induced signaling and interacts with RNF115, we next investigated the role of RNF115 in RNA virus-triggered signaling." (PMID 33139700, 2020). "It has been demonstrated that RNF115 catalyzes the ubiquitination of a series of proteins to modulate several signaling pathways and thereby regulates multiple processes such as cell proliferation, tumorigenesis, autophagy, and viral infections." (PMID 38129372, 2023). "Interestingly, we found that expression of RIG-I impaired RNF115–MAVS but not RNF115–MAVS–TM(VAMP-2) associations, indicating that RIG-I competitively engages MAVS against RNF115 on the mitochondria which might be responsible for the disassociation of RNF115 from MAVS after viral infections." (PMID 33139700, 2020). "Here we show that RNF115 plays dual roles in response to RNA or DNA virus infections by catalyzing distinct types of ubiquitination of MAVS and MITA at different phases of viral infection." (PMID 33139700, 2020). "Taken together, these results suggested that RNF115 constitutively interacts with MAVS and viral infection leads to their disassociation." (PMID 33139700, 2020). "We next examined the subcellular localization of RNF115 by cell fractionation and confocal microscopy assays in the presence or absence of viral infections." (PMID 33139700, 2020). "Finally, we provide data that highlight the molecular mechanism of RNF115-mediated dual roles in antiviral signaling by regulating homeostatic MAVS in uninfected cells and by promoting the activation of MITA after viral infection." (PMID 33139700, 2020). "Recently, it has been demonstrated that a fraction of RNF115 is located on mitochondria in primary mouse cells as revealed by cell fractionation assays and immunogold staining and electron microscopy analyses, and that the mitochondrial localization of RNF115 is not affected by viral infections." (PMID 35844553, 2022). "However, viral infection did not lead to disappearance of RNF115 from the mitochondrial fractions or mitotracker, suggesting that viral infection-resulted impairment of RNF115 and MAVS association is not due to disassociation of RNF115 from mitochondria." (PMID 33139700, 2020). "Consistently, the protein levels of MAVS are substantially increased in Rnf115−/− organs or cells without viral infection, and HSV-1-induced aggregation of MITA is impaired in Rnf115−/− cells compared to the wild-type counterparts." (PMID 33139700, 2020).
lung carcinoma (5 papers, 2021 to 2024). "In contrast, however, another study has reported that RNF115 induces ubiquitination and degradation of c-Myc and thereby inhibits H1299 lung cancer cell growth." (PMID 35844553, 2022). "However, information about the function of RNF115 in lung cancer, especially in LUAD, is still limited." (PMID 33509267, 2021).
Autoimmunity (3 papers, 2022 to 2025). The occurrence of an immune reaction against the organism's own cells or tissues. "Therefore, the RNF115 knockout mice are more resistant to bacterial infections and sensitive to imiquimod-induced autoimmunity." (PMID 35844553, 2022). "In addition, considering that MITA plays essential roles in self DNA-induced autoimmunity and tumor immunity, it is of great interest to examine whether and how RNF115 regulates autoimmunity and tumorigenesis in the future." (PMID 35844553, 2022). "Taken together, these data suggest that RNF115 negatively regulates TLR‐mediated antimicrobial immune responses and autoimmunity in vivo." (PMID 35343654, 2022). "For example, RNF115 negatively regulates TLRs-mediated signaling and autoimmunity and targeting RNF115 might promote TLR4-related sepsis or TLR7/9-related autoimmunity." (PMID 35844553, 2022).
gastric cancer (3 papers, 2020 to 2024). A primary or metastatic malignant neoplasm involving the stomach. "We additionally show that high expression levels of RNF115 mRNA correlate with poor prognosis in gastric cancer patients." (PMID 32980859, 2020). "In vitro and in vivo investigation demonstrated that RNF115 knockdown in gastric cancer cells can decrease cell growth and reduce tumorigenicity in a xenograft model." (PMID 32980859, 2020). "The in vivo effects of RNF115 were evaluated using a gastric cancer xenograft model established in BALB/C nude mice." (PMID 32980859, 2020). "In addition, RNF115 silencing can inhibit the tumorigenicity and metastasis of gastric cancer cells." (PMID 32980859, 2020). "Low levels of RNF115 mRNA correlated with better overall survival in gastric cancer patients, indicating that decreased expression of RNF115 may be a favorable prognostic indicator in patients with gastric cancer." (PMID 32980859, 2020). "This phenomenon may be related to the blockade of autophagy, suggesting that the inactivation of RNF115 exerted antitumor activity in gastric cancer cells." (PMID 32980859, 2020). "We also show that blocking autophagy by inactivating RNF115 inhibits the growth of gastric cancer cells in vitro and in vivo, which maybe a potential therapeutic target for cancers." (PMID 32980859, 2020). "Furthermore, the low levels of RNF115 mRNA in gastric tissues correlated to better prognosis in patients with gastric cancer, indicating that the expression of RNF115 may be a potential independent prognostic factor for patients with gastric cancer." (PMID 32980859, 2020). "Importantly, we provide in vitro and in vivo evidence that RNF115 inactivation inhibits the tumorigenesis and metastasis of BGC823 gastric cancer cells." (PMID 32980859, 2020).
HIV-1 infection (3 papers, 2017 to 2022). The type species of lentivirus and the etiologic agent of acquired immunodeficiency syndrome (AIDS). "Several studies have suggested that RNF115 is a restriction factor for HIV-1 infection." (PMID 35844553, 2022). "Our identification of RNF115 as a modifier for K63-linked ubiquitination and aggregation of MITA provided another layer to its restriction of HIV-1, indicating that RNF115 is a target for treatment of HIV-1 infection." (PMID 33139700, 2020).